TNF (tumor necrosis factor)
Diseases named in the same sentence as TNF in open-access papers (continued):
Sharing a sentence is not in itself a finding about the gene and the disease.
Insulin resistance (continued). "Interestingly, in vivo studies also confirmed kaempferol ameliorates insulin resistance through inhibiting pro-inflammatory responses, particularly by reducing NF-κβ, TNF-α, and IL-6 levels, and restoring insulin resistance by inhibiting phosphorylation of IRS-1." (PMID 32694996, 2020). "ASX treatment was also reported to ameliorate insulin resistance and improve insulin signaling by activating post-receptor insulin signaling, to reduce the oxidative stress produced by various stimuli including TNF-α, and to inhibit pro-inflammatory cytokines in obese mice." (PMID 32260306, 2020). "However, after adjustments, the relationship between TNF-α and insulin resistance disappeared." (PMID 33292292, 2020). "Hypertrophic adipocytes can produce pro-inflammatory cytokines, such as IL-6 and TNF, which leads to increased vascular permeability, circulating monocytes and the recruitment of cytotoxic T cells, initiating an inflammatory process that promotes insulin resistance." (PMID 33349270, 2020). "Similarly, insulin resistance exhibits a positive relationship with IL-6 and TNF levels." (PMID 33327502, 2020). "Studies have provided preclinical proof of concept that induction of bergamot may improve the phenotypical and morphological features of NASH along with reduction in adipose tissue inflammation and inflammatory cytokines, IL-6 and TNFα, hypoadiponectinemia, insulin resistance and dyslipidemia." (PMID 32903449, 2020). "Indeed, the plant extract may act as antagonist of TNF-α and IL-1β leading to the reduction of insulin resistance and to antihyperglycemia effects as observed in the study." (PMID 33293987, 2020). "Moreover, gut barrier dysregulations and pathologies promote the production of proinflammatory cytokines (IL-6 and TNF-α), which in turn trigger subclinical inflammation and insulin resistance, shedding light again on the inflammation loop between CRC and diabetes." (PMID 32664279, 2020). "Furthermore, TNF-α stimulates macrophages to release metalloproteinases, which leads to accelerated degradation and destabilization of the fibrous cover of atherosclerotic plaques, triggering dyslipidemia, insulin resistance, and endothelial dysfunction." (PMID 32587660, 2020). "Therefore, we treated adipocytes with TNF-α, which dramatically increased the expression of genes involved in insulin resistance in adipocytes, such as IL-6, CCL2, and chemokine ligand 9 (CCL9), but significantly reduced glucose transporter 4 (GLUT4) expression." (PMID 32024237, 2020). "Pro-inflammatory adipokines (IL-6, TNF-α, MCP-1) and leptin, associated with the maintenance of the obese state, are elevated during the obese state whereas adiponectin, which plays an important role in insulin sensitivity, is decreased, connecting its role to insulin resistance and T2DM." (PMID 32903449, 2020). "In addition, decreased insulin resistance can lead to lower levels of proinflammatory cytokines, including tumor necrosis factor-alpha, interleukin-6, leptin, and chronic hepatic inflammatory markers, which have been associated with liver diseases including liver cancer." (PMID 33271947, 2020). "DUSP9 may inhibit insulin resistance by antagonizing the effects of tumor necrosis factor-α." (PMID 31772940, 2019). "However, it was found that, in obese conditions, adipocytes synthesize and secrete pro-inflammatory cytokines (IL-1, IL-6, and TNF-α), and they are involved in several metabolic pathways related to insulin resistance, ROS production, lipoprotein lipase activity, and adipocyte function." (PMID 31597283, 2019). "Thus, we speculate that the anti-inflammatory effect of FGF-1 is strong and able to block inflammation in TNF-α-induced insulin resistance, resulting in similar protective effects in both models." (PMID 31866871, 2019).
Insulin resistance (continued). "Furthermore, considering TNF-α is an important contributing factor to the development of insulin resistance, additional studies are warranted to determine the precise role of EWH and IRW in relation with the action of increased circulating TNF-α in insulin resistance animals." (PMID 29955954, 2019). "However, the overall effect of resistin was not significant in people with low resistin levels, several other factors may dominate insulin resistance like free fatty acids, hyperosmotic stress, and TNF-α." (PMID 31803062, 2019). "Thus, TNF-α may be produced in the placenta and skeletal muscle to induce or exacerbate insulin resistance." (PMID 31828161, 2019). "In addition, it has been observed that the pro-inflammatory cytokine TNF may promote insulin resistance by phosphorylation of the insulin receptor." (PMID 31382516, 2019). "Preliminary evidence suggests that elevated levels of certain adipocytokines [e.g., leptin, visfatin, tumor necrosis factor-α (TNF-α), and interleukin-1] and increased oxidative stress, occurring during some conditions of hypothyroidism, may concur with the development of insulin resistance." (PMID 31212642, 2019). "Consequently, especially persons suffering from pre-diabetes may benefit from these alterations as TNF-α mediated low-grade inflammation is co-responsible for the development of insulin resistance." (PMID 31214051, 2019). "High-fat diets, in particular diets rich in SFAs, may promote insulin resistance through several mechanisms, such as insulin signaling interfering, the promotion of inflammation through tumor necrosis factor alpha (TNF-α) production, and increased oxidative stress." (PMID 30717458, 2019). "Thus, TNF-α, a pro-inflammatory cytokine, plays a central role in some types of insulin resistance." (PMID 31635166, 2019). "TNF-α is a potent inflammatory cytokine, released from macrophages and T lymphocytes, with important functions on DM, since it not only plays an important role in the development of insulin resistance, but also in progression to microvascular complications of DM." (PMID 31652638, 2019). "Moreover, they suggest putative interactions between FGF23 and inflammatory regulatory pathways due to its association with comorbidities of psoriasis like insulin resistance, dyslipidemia, atherosclerosis, or markers of chronic inflammation like interleukin-6, CRP, TNFα, and fibrinogen." (PMID 31847236, 2019). "In addition, several reports have indicated that high circulating concentrations of inflammatory mediators (including CRP, IL-6, TNF-α, and MCP-1) originate from obese adipose tissue and that the levels of these mediators are associated with the degree of insulin resistance." (PMID 31192262, 2019). "To test our hypothesis, we established the TNF-α-induced insulin resistance cell model." (PMID 31591391, 2019). "However, patients with diabetes exhibit increased synovial levels of TNF-α and macrophages, suggesting that insulin resistance may impair the protective effect of insulin in the joint, and greater insulin resistance is related to lower femoral neck strength." (PMID 29527173, 2018). "In mature 3T3-L1 adipocytes, TNF-α-induced insulin resistance was accompanied by a variety of changes in the sugar chain structure, including the increase in the expression of β4GalT5, suggesting that β4GalT5 might also be involved in the inflammatory response process." (PMID 29546034, 2018). "Furthermore, NF-κB activation increases the transcription of IL-1β, IL-6, and TNF-α and hyperexpression of these mediators may contribute to insulin resistance." (PMID 29760586, 2018). "As recent studies have indicated that agents capable of improving insulin sensitivity may be of great value in the treatment of T2DM, it is highly important to investigate whether insulin resistance and its clinical correlates can be reversed using therapies aimed at the neutralisation of TNF-α." (PMID 30914847, 2018).
Insulin resistance (continued). "In addition TNF-α is known to promote insulin resistance and stimulate TGF-β gene expression." (PMID 28575190, 2018). "Notably, insulin resistance and lipolysis are both mediated by TNF." (PMID 27900559, 2017). "Thus, inflamed adipose tissue could promote low-grade systemic inflammation by releasing proinflammatory cytokines and chemokines (IL-1ß, TNF-α, IL-6, leptin, CCL2, CCL3, and CXCL8) and causing insulin resistance and endothelial dysfunction." (PMID 28512338, 2017). "In the present study, we discovered that TNF-α might stimulate PA transcytosis across cardiac microvascular endothelial cells, which further impaired the insulin-stimulated glucose uptake by cardiomyocytes and promoted insulin resistance." (PMID 28304381, 2017). "In addition, subjects with elevated blood glucose were generally companied with insulin resistance, which may result in higher level of pro-inflammatory cytokines, such as tumor necrosis factor-alpha (TNF-α) and interleukin-6 (IL-6)." (PMID 28432278, 2017). "Several additional conditions often accompanying the syndrome were also present: insulin resistance (increased plasma insulin), kidney damage (increased plasma creatinine and albuminuria) and inflammation (increased plasma levels of TNF-α and interleukin six (IL-6))." (PMID 28101123, 2017). "Therefore, TNF-α, IL-1β and IL-6 secretion under high fructose consumption may account for insulin resistance, chronic inflammation and endothelial dysfunction in local tissues and organs." (PMID 28353649, 2017). "In addition, Se may reduce insulin resistance through inhibiting the activity and the production of inflammatory cytokines including tumour necrosis factor-a (TNF-a), nuclear factor-kappa B (NF-κB) and interleukin (IL-1 and IL-18)." (PMID 28380029, 2017). "Moreover, the tendency shown for decreased fasting glucose in the TTI treated group might be explained by TNF-α reduction, which decreases insulin resistance." (PMID 27690087, 2016). "Moreover, the secretion of various adipokines, such as tumor necrosis factor α (TNFα), interleukin-6 (IL-6), and adiponectin may play a role in the relation between insulin resistance and the development of HCC." (PMID 26913058, 2016). "Similar to the findings in mice we could also demonstrate that TNFα and CCL3 levels correlated with fasting glucose HOMA-IR and NAFLD severity suggesting that similar pathogenic mechanisms may underlie the development of insulin resistance and NASH in humans." (PMID 27992443, 2016). "It is possible that restricting AGE intake could be beneficial in reducing levels of some inflammatory markers, such as TNFα, which could help to prevent or slow the progression of chronic conditions, such as insulin resistance or atherosclerosis however further high quality evidence is required." (PMID 26938557, 2016). "Supporting this hypothesis, two reports indicated that pioglitazone, a peroxisome proliferator-activated receptor-γ (PPARγ) agonist reduced TNF-α-mediated IRS1Ser307 phosphorylation and insulin resistance in diabetic rat retinas, with a concomitant improvement in retinal function." (PMID 27514532, 2016). "TNFα-induced insulin resistance in brown adipocytes could be in part mediated by ceramide." (PMID 26903879, 2016). "Moreover, CAT prevented TNF-α-induced insulin resistance in 3T3-L1 adipocytes." (PMID 27023799, 2016). "Then, we examined whether ILG inhibits TNF-α-induced insulin resistance in adipocytes." (PMID 26975571, 2016). "In addition, we investigated whether TNF-α triggers PTEN-mediated vascular insulin resistance in HFD-fed animals." (PMID 27562094, 2016). "In addition, pioneering studies have established that activation of pro-inflammatory TNF-α is a key mechanism leading to peripheral insulin resistance in diabetes and that inhibition of hypothalamic inflammation prevents peripheral insulin resistance." (PMID 25617315, 2015).
Insulin resistance (continued). "An IRS-1 Ser 307 mutation was shown to protect against tumor necrosis factor alpha induced inhibition of IRS-1 tyrosine (Tyr) phosphorylation via the JNK kinase pathway; thus, Ser 307 phosphorylation is frequently cited as a cause of stress-induced insulin resistance." (PMID 25978724, 2015). "However, the mechanisms linking TNF-α to hepatic insulin resistance remain poorly understood." (PMID 26666849, 2015). "In addition, IL-6 has strong anti-inflammatory effects and may inhibit TNF-α induced insulin resistance." (PMID 25853572, 2015). "It is now known that the plasma levels of pro-inflammatory cytokines, such as TNF-α, IL-6 or IL-1β, and chemokines are elevated in T2D patients, while in vivo studies have revealed that inhibition of key inflammatory cytokines protects rodents from insulin resistance." (PMID 26300887, 2015). "Thus, elevated local and/or circulating levels of TNF-α may contribute directly to myocardial insulin resistance." (PMID 26659007, 2015). "Indeed, ROS, IL-6 and TNFα were reported to impair the normal differentiation of preadipocytes and lipid accumulation contributing to inflammation-induced adipose tissue dysregulation and insulin resistance." (PMID 25685071, 2015). "As the potential effector molecules involved in insulin resistance, the levels of mTOR, phosphorylated mTOR and downstream phosphorylated S6K were increased in the TNF-α and IL-6-treated groups, suggesting that the mTOR/S6K pathway may be involved in insulin resistance under inflammatory stress." (PMID 26449763, 2015). "However, high concentrations of TNF-α could also be implied in the development of metabolic abnormalities such as insulin resistance." (PMID 24741627, 2014). "Resistin and TNF-α secreted by adipose tissue may also play roles on regulate insulin resistance." (PMID 24684833, 2014). "Indeed, insulin resistance in RA patients was shown to be higher than that observed in patients with systemic lupus erythematosus, and was correlated with serum levels of IL-6, TNFα, and C-reactive protein (CRP)." (PMID 25988122, 2014). "Furthermore, IL-1β may constitute a cell-cell mediator in metainflammation, as IL-1β produced by TNFα-stimulated mouse adipocytes has been shown to induce insulin resistance in liver cells." (PMID 24918199, 2014). "Moreover, TNF-α may directly downregulates adiponectin contributing to the development of vascular insulin resistance and the decrease of UCP-2 levels in the aorta." (PMID 25077985, 2014). "In addition, it has been reported that TNF-α is overexpressed in the adipose and muscle tissues of obese and insulin-resistant non-diabetic subjects, and overexpression is positively correlated with insulin resistance." (PMID 25548896, 2014). "Hence, TNF-α is more likely to exert crucial effects on insulin resistance during pregnancy." (PMID 25202741, 2014). "However, a positive correlation of TNF expression, IL1 mRNA, and body condition score (BCS) of horses was demonstrated in another study, in which an increased cytokine expression seemed to be a risk factor for the development of insulin resistance." (PMID 24894908, 2014). "Additionally, adipocytokines like TNF-α, serine kinases and free fatty acids are among the many factors and channels that may contribute to insulin resistance, type II diabetes mellitus, and other diseases." (PMID 24324517, 2013). "The administration of HCD in piglets has been associated with hepatic steatosis, insulin resistance, and hepatic inflammation, including increased myeloperoxidase activity and expression of proinflammatory cytokines and chemokines, particularly IL-2, CXCL2, TNFα, and IL-6." (PMID 23565157, 2013). "Curcumin improved peripheral insulin resistance in insulin-resistant ob/ob mice with steatosis by reducing NF-κB/RelA DNA-binding activity, decreasing mRNA level of TNF and IL-6, and enhancing IL-4 production in hepatic TNF/iNOS-producing dendritic cells and adipose tissue macrophages." (PMID 24348712, 2013).
Insulin resistance (continued). "The Atherosclerosis and Insulin Resistance (AIR) Study reported that ox-LDL levels were associated with both subclinical atherosclerosis, as assessed by ultrasonography, and inflammatory markers, including C-reactive protein (CRP) and tumor necrosis factor-α TNF-α." (PMID 24455214, 2013). "Subsequently, the same research group demonstrated that TNFα suppressed insulin signaling by inhibiting insulin receptor tyrosine kinase activity and proposed a model in which inflammation defined as an increased level of TNFα in adipose tissue could be the basis of systemic insulin resistance." (PMID 23964268, 2013). "Moreover, the treatment of TNF-α induces hepatic insulin resistance in obese Zucker rats." (PMID 24349514, 2013). "Given that TNF-α and IL-6 as well as the NF-κB activation are crucial for the development of glucose intolerance and insulin resistance, our data support the notion that inhibition of inflammation-related NF-κB activation may be a promising strategy for the intervention of glucose intolerance." (PMID 23326455, 2013). "Amongst several mediators, tumor necrosis factor (TNF) and interleukin-6 (IL-6) were shown to promote both insulin resistance and cardiac hypertrophy, suggesting that inflammation in metabolic syndrome might be a central feature in atherogenesis as well as in cardiac hypertrophy." (PMID 23365487, 2013). "Consequently, anti-TNF agents may be preferred as first-line biologic treatment in patients with active RA and high inflammatory burden, and metabolic abnormalities or insulin resistance." (PMID 22691241, 2012). "Moreover, TNF-α is known to directly inhibit insulin signaling, resulting in insulin resistance." (PMID 23155382, 2012). "With the onset of diabetes, adipokines such as TNF-α and IL-6 may contribute to insulin resistance." (PMID 23267348, 2012). "We tested whether TNF-α inhibition could prevent insulin resistance in adipose tissue." (PMID 22816003, 2012). "As TNFα treatment may induce insulin resistance by reactivating the expression of preadipocyte genes in vitro this may be the reason why the majority of miRNAs found in our study are oppositely regulated in differentiated, insulin-sensitive adipocytes and insulin resistant ob/ob mice." (PMID 21731698, 2011). "Both TNFα and nonesterified acids (NEFAs) can cause metabolic and endothelial insulin resistance." (PMID 20634940, 2010). "The possible molecular mechanism of TNF-α-induced insulin resistance may involve IRS-1." (PMID 18604303, 2008). "Thus, anumber of studies indicate that elevated TNF-α is not secondary to thepathological conditions associated with insulin resistance, but that TNF-αplays a direct pathogenic role in glucose metabolism." (PMID 19148295, 2008). "Additional modelling for TNFα, resistin, catecholamine infusion rate, age, gender, BMI, operation time, heart/lung bypass time or medication did not further improve the model, suggesting minor contribution of these parameters to the development of insulin resistance in our model." (PMID 19087258, 2008). "Resistin and other molecules commonly called adipokines, such as TNF-α, IL-6, and visfatin,are produced and secreted by both adipocytes and macrophages, and have beensuggested to be important players in the pathogenesis of insulin resistance andatherosclerosis." (PMID 19125180, 2008). "Circulating FGL2 positively correlated with glycemic indices, insulin resistance, lipid parameters, renal tubular injury markers (NGAL, KIM-1), inflammatory cytokines (TNF-α, IL-6), and fibrotic mediators (TGF-β1, CTGF)." (PMID 42161877, 2026). "A higher proportion of women with EIN/EC exhibited elevated insulin resistance, hs-CRP, IL-6/TNF-α, and MDA levels compared with the leiomyoma group." (PMID 41595367, 2026). "Pro‐inflammatory macrophages, characterized by elevated expression of CD11c+ and Nos2, secrete inflammatory cytokines such as TNF‐α, IL‐6, and IL‐1β, thereby inhibiting GLUT4 expression and worsening insulin resistance." (PMID 41509193, 2026).